EGFR (epidermal growth factor receptor)
Diseases named in the same sentence as EGFR in open-access papers (continued):
Sharing a sentence is not in itself a finding about the gene and the disease.
non-small cell lung carcinoma (continued). "Among EGFR-TKIs, gefitinib and erlotinib have been extensively evaluated in non-small cell lung cancer (NSCLC), and sensitivity to these drugs has been associated with the presence of somatic mutations in the EGFR kinase domain or with EGFR amplification." (PMID 18253126, 2008). "They analyzed the profiles of eight non-small cell lung carcinoma (NSCLC) cell lines with known EGFR mutation status to identify genes regulated by constitutive activation of the receptor." (PMID 19517027, 2008). "In non-small-cell lung carcinoma (NSCLC) cells with mutated EGFR, amplification of the MET oncogene activates prosurvival ErbB3 signaling, which allows escape from tyrosine kinase inhibition." (PMID 19019207, 2008). "TKI is particularly effective against a subset of non-small cell lung cancers (NSCLCs) that have several somatic mutations in the EGFR tyrosine kinase domain." (PMID 17931419, 2007). "Epidermal growth factor receptor (EGFR) mutations are present in the majority of patients with non-small cell lung cancer (NSCLC) responsive to the EGFR tyrosine kinase inhibitors (TKIs) gefitinib or erlotinib." (PMID 17973572, 2007). "ErbB2 heterodimerises with EGFR and ErbB2 mutations have recently been reported within a subset of non-small cell lung cancer (NSCLC)." (PMID 17224925, 2007). "Activating somatic mutations in epidermal growth factor receptor (EGFR) confer unique biologic features to non-small cell lung cancer (NSCLC) cells, but the transcriptional mediators of EGFR in this subgroup of NSCLC have not been fully elucidated." (PMID 18030354, 2007). "The aim of this study was to evaluate the usefulness of EGFR mutation status in serum DNA as a means of predicting a benefit from gefitinib (IRESSA) therapy in Japanese patients with non-small cell lung cancer (NSCLC)." (PMID 17848912, 2007). "Three recent studies have demonstrated that gefitinib, another EGFR TK inhibitor, induced dramatic clinical responses in non-small-cell lung cancers with activating mutations within the EGFR kinase domain." (PMID 16570047, 2006). "Several studies showed that gain-of-function somatic mutations affecting the catalytic domain of EGFR in non-small cell lung carcinomas were associated with response to gefitinib and erlotinib, both EGFR-tyrosine kinase inhibitors." (PMID 17150109, 2006). "Epidermal growth factor receptor (EGFR) mutations are strong determinants of tumour response to EGFR tyrosine kinase inhibitors in non-small-cell lung cancer (NSCLC)." (PMID 17060940, 2006). "We conducted a phase II trial to evaluate the efficacy and safety of gefitinib as first-line therapy for advanced non-small cell lung cancer (NSCLC) with EGFR mutations." (PMID 17047648, 2006). "We then screened for KRAS mutations in 30 non-small cell lung cancer biopsies that had been previously sequenced for mutations in EGFR exons 18–21." (PMID 17184525, 2006). "However, its predictive role for treatment response in epidermal growth factor receptor (EGFR)-mutated non-small cell lung cancer (NSCLC) remains debated." (PMID 41682625, 2026). "Furthermore, membrane HER3 was upregulated by tyrosine kinase inhibitor treatment in non-small-cell lung cancer cell lines harboring specific driver mutations, including EGFR-activating mutations, ROS1 fusions, and ALK fusions." (PMID 41752065, 2026). "Non-small cell lung cancer (NSCLC) with EGFR L833V/H835L in cis mutation remains poorly understood." (PMID 42018150, 2026). "This study presents a comprehensive machine learning approach that integrates clinical data, CT-derived morphological indicators, and radiomic signatures to enable the non-invasive prediction of EGFR mutation status in individuals diagnosed with non-small cell lung cancer (NSCLC)." (PMID 41149132, 2025).
non-small cell lung carcinoma (continued). "Similarly, changes in the expression of targets like epidermal growth factor receptor (EGFR) in non-small cell lung cancer can lead to resistance to EGFR inhibitors, as mutations or overexpression can alter drug binding, rendering the therapy less effective." (PMID 40867257, 2025). "EGFR overexpression is correlated with the risk of metastasis, resistance to chemotherapy, and poor survival for patients with breast cancer, some types of melanoma, head and neck squamous cell carcinoma, and non-small cell lung carcinoma." (PMID 40943484, 2025). "Similar findings have been described for patients with EGFR-positive non-small cell lung cancer, where the clonal dominance of EGFR mutations was an independent factor of EGFR tyrosine kinase inhibitor benefit following an analysis of LB, and patients with clonal EGFR mutations exhibited longer PFS." (PMID 40244273, 2025). "Similarly, EGFR mutations in non-small cell lung cancer (NSCLC) have been linked to metabolic activity alterations that can be traced on positron emission tomography (PET) scans." (PMID 40722321, 2025). "Currently, three generations of EGFR tyrosine kinase inhibitors (TKIs) are used in the treatment of non-small-cell lung cancer (NSCLC) patients with activating mutations in the EGFR gene, and ongoing clinical trials examine the safety and effectiveness of new third- and fourth-generations." (PMID 40002158, 2025). "For example, selective inhibition of CK1α using D4476 inhibits autophagy flux, potentially suppressed the proliferation and the metastasis of RAS-mutated human CRC HCT116 cells, EGFR-mutant Non-small cell lung cancer (NSCLC), and human multiple myeloma U-266 cells." (PMID 41234632, 2025). "Interestingly, the homologous EGFR p.L747P mutation confers resistance to gefitinib in patients with non-small cell lung cancer." (PMID 41009670, 2025). "cGAS mRNA expression was correlated with CIN in EGFR-mutated non-small-cell lung cancer." (PMID 40136696, 2025). "The therapeutic landscape for advanced non-small cell lung cancer (NSCLC) harboring common EGFR mutations - namely exon 19 deletions (ex19del) and L858R substitutions - has significantly evolved, with osimertinib becoming the global first-line standard following the pivotal FLAURA trial." (PMID 41174254, 2025). "Grade 3–4 osimertinib-induced interstitial lung disease in epidermal growth factor receptor-mutated non-small cell lung cancer significantly reduced survival compared to lower grades, with substantial interstitial lung disease recurrence risk upon subsequent therapy." (PMID 39703157, 2025). "Key gaps and needs in EGFR-mutated non-small-cell lung cancer." (PMID 39237103, 2025). "We provide a comprehensive analysis of recent artificial intelligence–based approaches for predicting epidermal growth factor receptor (EGFR) mutation status in non-small cell lung cancer (NSCLC), detailing the research methods, data modalities, and model performance." (PMID 40708937, 2025). "For example, patients with non-small cell lung cancer who have mutations in the gene that encodes EGFR (epidermal growth factor receptor) may be prescribed tyrosine kinase inhibitor (TKI) therapy." (PMID 41369346, 2025). "NTRK2 fusion coexisting with EGFR mutations is a rare molecular characteristic of non-small cell lung cancer, accompanied by positive PD-L1 expression, and may serve as a promising biomarker for targeted therapy." (PMID 41383499, 2025). "Moreover, epidemiological studies have demonstrated that the prevalence of epidermal growth factor receptor (EGFR) mutations in non-small cell lung cancer (NSCLC) varies significantly across geographic regions." (PMID 40563596, 2025). "Osimertinib, a third-generation epidermal growth factor receptor (EGFR) tyrosine kinase inhibitor, is a first-line therapy for advanced or metastatic non-small cell lung cancer (NSCLC) with EGFR mutations, including both sensitizing and T790M resistance mutations." (PMID 39703183, 2025).
non-small cell lung carcinoma (continued). "EGFR-TKIs have opened a crucial therapeutic avenue for EGFR-sensitive mutated non-small cell lung cancer (NSCLC) but evolution of resistance limits longer term effectiveness of these treatments, with multiple combination treatments and follow-on therapy options being explored." (PMID 41425618, 2025). "For example, identifying activating epidermal growth factor receptor (EGFR) mutations in non-small cell lung cancer patients enables clinicians to select EGFR inhibitors for those most likely to respond, thereby improving outcomes while minimizing unnecessary toxicity." (PMID 41301080, 2025). "Interestingly, mitochondrial EGFR has been implicated in regulating mitochondrial dynamics, particularly in non-small-cell lung cancer (NSCLC)." (PMID 41145430, 2025). "Mutations of EGFR have been identified as a cause of non-small-cell lung cancer (NSCLC), overexpression of HER2 is associated with breast cancer, and mutations of KIT (V-kit Hardy-Zuckerman 4 feline sarcoma viral oncogene homolog) are implicated in gastrointestinal stromal tumours." (PMID 40563591, 2025). "To contextualize our clinical findings within the broader scientific landscape, we conducted a bibliometric analysis using CiteSpace software to explore global publication trends on EGFR exon 20 insertion (ex20ins) mutations in non-small cell lung cancer (NSCLC) from January 2000 to October 2023." (PMID 41585239, 2025). "This study suggests that post-progression retreatment with EGFR-TKIs is both effective and safe in patients with locally advanced non-small cell lung cancer harboring EGFR mutations who experienced disease progression after initial gefitinib induction and chemoradiotherapy." (PMID 40704256, 2025). "For instance, drugs targeting activating mutations in the epidermal growth factor receptor (EGFR), such as gefitinib, have shown significant efficacy in patients with non-small cell lung cancer, particularly among those with radon-associated tumors harboring these alterations." (PMID 40427695, 2025). "We had previously conducted a phase II study (LOGIK0902/OLCSG0905 study) involving the eight-week administration of gefitinib, followed by cisplatin-based chemoradiotherapy, to treat locally advanced, epidermal growth factor receptor (EGFR)-mutated, non-small cell lung cancer (NSCLC)." (PMID 40704256, 2025). "For example, EGFR inhibitors are also utilized in treating non-small cell lung cancer (NSCLC), but there is a risk of developing resistance mutations, like T790M, which may necessitate subsequent rounds of treatment using new drugs." (PMID 40427686, 2025). "In this study, we investigated eccDNA in non-small cell lung cancer (NSCLC) by sequencing plasma eccDNA from 32 epidermal growth factor receptor (EGFR)-mutated NSCLC patients before and during treatment with osimertinib, as well as plasma eccDNA from five healthy individuals." (PMID 41165514, 2025). "More specifically, human epidermal growth factor receptor 2 (HER2) is linked to breast cancer, alpha-fetoprotein to hepatocellular carcinoma, and the increased expression of epidermal growth factor receptor (EGFR) on EVs correlates with a higher risk of non-small cell lung cancer." (PMID 39776815, 2025). "This study aimed to investigate whether these factors affect the overall survival (OS) of patients with epidermal growth factor receptor (EGFR) mutation-positive non-small cell lung cancer (NSCLC) using Tokushukai REAL World Data." (PMID 39673402, 2025). "This is evidenced by a significantly higher prevalence of pathogenic EGFR gene mutations in Chinese patients with non-small cell lung cancer (NSCLC) compared to other ethnic groups, underscoring the necessity for precision-based prevention and control strategies." (PMID 41451103, 2025).
non-small cell lung carcinoma (continued). "For instance, non-small cell lung cancers (NSCLCs) harboring activating EGFR mutations frequently develop the T790M substitution upon prolonged exposure to first- or second-generation EGFR tyrosine kinase inhibitors (TKIs), drastically diminishing drug binding affinity." (PMID 40227591, 2025). "The treatment of non-small-cell lung cancer (NSCLC) patients with epidermal growth factor receptor (EGFR) mutations radically changed after the introduction of EGFR tyrosine kinase inhibitors (TKIs) to clinical practice, both in a metastatic setting and in earlier stages of disease." (PMID 40002263, 2025). "Despite significant survival improvements from third-generation epidermal growth factor receptor tyrosine kinase inhibitors (EGFR-TKIs) in patients with advanced EGFR-mutated non-small cell lung cancer (NSCLC), almost all patients eventually develop resistance." (PMID 40860888, 2025). "EGFR (epidermal growth factor receptor) gene mutations are the most common targetable driver mutations seen in up to 32.3% of non-small-cell lung cancer (NSCLC) patients, and targeted therapies that improve survival highlight the need for early molecular diagnosis." (PMID 41141063, 2025). "Background and Clinical Significance: Non-small-cell lung cancer (NSCLC) with EGFR mutations, particularly de novo compound mutations such as exon 19 deletions (Ex19del) with T790M substitutions, present a significant clinical challenge due to resistance to many treatments." (PMID 40700234, 2025). "This study aimed to directly compare the relative risk (RR) of hepatotoxicity between new-generation (afatinib, osimertinib, dacomitinib) and first-generation (gefitinib, erlotinib) EGFR-TKIs in non-small-cell lung cancer (NSCLC) and to evaluate their overall risk-benefit profile." (PMID 41462168, 2025). "In addition, mutations and abnormal expression of EGFR have been observed in different cancer types, including glioblastomas, non-small cell lung cancer (NSCLC), breast cancer, and ovarian cancer." (PMID 38202856, 2024). "Epidermal growth factor receptor (EGFR) mutations are commonly found in non-small cell lung cancer." (PMID 39767566, 2024). "Importantly, the reduced exposure remained above the inhibitory concentration for EGFR mutations in non-small-cell lung cancer, indicating that the drug’s efficacy would likely remain intact in clinical settings." (PMID 39598538, 2024). "Mutations in EGFR may cause uncontrolled growth and proliferation of cells, especially in non-small-cell lung cancer (NSCLC)." (PMID 39205175, 2024). "Since EGFR mutations are common in non-small-cell lung cancer and are associated with cancer cell proliferation, these miRNA–gene correlations may be crucial for developing novel cancer therapies." (PMID 39684787, 2024). "While tyrosine kinase inhibitors (TKIs) targeting mutant epidermal growth factor receptor (EGFR) have improved the survival of patients with non-small cell lung cancer (NSCLC) in the last decade, NSCLC patients with mutated EGFR are more likely to spread to the brain than those with wild-type EGFR." (PMID 38589859, 2024). "According to the findings, somatic EGFR mutations can be employed as a diagnostic tool for non-small cell lung cancer in Egypt, and they can be implemented in conjunction with clinical criteria to identify which patients are more likely to respond favorably to TKIs." (PMID 39710832, 2024). "Among non-small cell lung cancer patients, approximately 30%–40% of Asian patients have EGFR mutations, approximately 90% of which are exon 19 deletion mutations (Del19) and exon 21 L858R mutations, accounting for 44%–51% and 38%–40% of all mutations, respectively." (PMID 39777265, 2024).
non-small cell lung carcinoma (continued). "Patients with advanced non-small cell lung cancer who present with the T790M mutation may have a better chance of surviving if they take ocitinib, a very potent and selective EGFR mutant inhibitor." (PMID 38957318, 2024). "Therefore, the treatment of EGFR-mutated non-small cell lung cancer should focus on solving EGFR-TKI resistance mutations." (PMID 39308869, 2024). "Non-small cell lung cancer patients with EGFR mutations had poor anti-PD-1/L1 efficacy." (PMID 39188712, 2024). "SMARCA4-deficient non-small cell lung cancer: Infiltrative poorly differentiated adenocarcinoma of the right lung with EGFR exon 21 L858R mutation, classified as stage IVB (cT3N2M1c) involving the right parietal lobe, right clavicle, and right sacroiliac joint." (PMID 39465834, 2024). "Through precise retrieval using the keywords “LJF and cancer,” we identified a notable single-arm clinical study titled “A single-arm clinical study of LJF oral liquid in the treatment of non-small cell lung cancer EGFR-TKIs-associated oral mucositis” with the patent number ChiCTR2400080982." (PMID 39314630, 2024). "The objective of this study was to compare the clinical outcomes of osimertinib as a 2nd-line treatment versus as a ≥3rd-line treatment in advanced and recurrent Epidermal Growth Factor Receptor (EGFR)-mutant non-small-cell lung cancer (NSCLC) patients with acquired T790M mutations." (PMID 39766072, 2024). "Some patients harbored several alterations as exemplified by a patient with EGFR-mutant non-small cell lung carcinoma where repeated CSF sequencing identified the emergence of multiple different EGFR mutations in response to first and third-generation EGFR inhibitors." (PMID 39289779, 2024). "The discovery of epidermal growth factor receptor (EGFR) somatic mutations and the availability of tyrosine kinase inhibitors (TKIs) as targeted therapies have transformed the treatment landscape for advanced non-small cell lung cancer (NSCLC)." (PMID 38638860, 2024). "A comprehensive case study involving 457 non-small cell lung cancer patients with EGFR mutations treated with EGFR tyrosine kinase inhibitors demonstrated that SAFE-MIL outperforms conventional regression methods in accuracy, effectively capturing inter-patient variability in risk." (PMID 39211737, 2024). "Outside of the realm of immune system directed therapies, other BiTE have been developed targeting surface proteins, such as amivantamab that has been approved for patients with non-small cell lung cancer harboring an epidermal growth factor receptor (EGFR) exon 20 insertion mutation." (PMID 38476371, 2024). "Moreover, erlotinib has been shown to be effective in improving progression-free survival in non-small cell lung cancer patients with EGFR mutation." (PMID 38448889, 2024). "Gefitinib (GEF), a hydrophobic tyrosine kinase inhibitor, disrupts cancer cell signalling and proliferation through epidermal growth factor receptor (EGFR) binding, warranting its approval for the treatment of non-small cell lung cancer with specific EGFR gene mutations." (PMID 38006449, 2024). "Overall, the fusion model shows promising performance in predicting EGFR mutation status and may have potential clinical utility in guiding treatment decisions for non-small cell lung cancer patients." (PMID 39619439, 2024). "Using different modeling approaches with or without consideration of brain metastasis, we compared the quality-adjusted life-year (QALY) estimates of Osimertinib and pemetrexed-platinum in advanced non-small cell lung cancer with epidermal growth factor receptor mutations." (PMID 38336654, 2024). "Here, we describe a simple, selective, and rapid non-cross linking detection assay, using approx. 35 nm spherical Au nanoprobes, for a common mutation occurring in exon 19 of the epidermal growth factor receptor (EGFR), associated with non-small-cell lung cancer cells." (PMID 38667155, 2024).